DDX39A (DExD-box helicase 39A)
Description:
Helicase that plays an essential role in mRNA export and is involved in multiple steps in RNA metabolism including alternative splicing. Regulates nuclear mRNA export to the cytoplasm through association with ECD. Also involved in spliceosomal uridine-rich small nuclear RNA (U snRNA) export by stimulating the RNA binding of adapter PHAX. Plays a role in the negative regulation of type I IFN production by increasing the nuclear retention of antiviral transcripts and thus reducing their protein expression. Independently of the interferon pathway, plays an antiviral role against alphaviruses by binding to a 5' conserved sequence element in the viral genomic RNA.
Synonyms: DDX39; DDXL; BAT1L; URH49; BAT1
Tractability: PROTAC: UniProt records ubiquitination sites on it; ubiquitination databases record sites on it; its protein half-life has been measured.
Target class: Enzyme; Hydrolase
Gene: Protein-coding gene on chromosome 19 (14,408,798 to 14,419,383, reverse strand). Ensembl gene ENSG00000123136.
Subcellular location: Nucleus; Cytoplasm
Subcellular location (Human Protein Atlas): Nuclear speckles
Pathways (Reactome):
Metabolism of RNA: Transport of Mature mRNA derived from an Intron-Containing Transcript; mRNA 3'-end processing
Gene Ontology:
Molecular function: ATP hydrolysis activity; identical protein binding; protein binding; RNA binding; ATP binding; nucleic acid binding; RNA helicase activity
Biological process: mRNA export from nucleus; mRNA splicing, via spliceosome; negative regulation of innate immune response; negative regulation of RNA export from nucleus; RNA export from nucleus
Cellular component: cytoplasm; membrane; nucleus; nucleoplasm; transcription export complex
Genetic constraint (gnomAD): Loss-of-function variants: 13 observed, 45.4 expected, observed/expected ratio (o/e) 0.29, 90% interval 0.19 to 0.46. The upper end of that interval is the gene's LOEUF score, 0.46, which puts it in group 2 of 6, group 1 being the genes least tolerant of losing a copy. Missense variants: 352 observed, 588.41 expected, observed/expected ratio (o/e) 0.6, 90% interval 0.55 to 0.65. Synonymous variants: 234 observed, 228.42 expected, observed/expected ratio (o/e) 1.02, 90% interval 0.92 to 1.14.
Homologues: Orthologues: chimpanzee DDX39A (100% identical), macaque DDX39A (100% identical), dog DDX39A (98% identical), mouse Ddx39a (97% identical), rat Ddx39a (97% identical), guinea pig DDX39A (96% identical), pig DDX39A (95% identical), zebrafish ddx39ab (92% identical), zebrafish ddx39aa (91% identical), tropical clawed frog ddx39a (90% identical), Drosophila melanogaster Hel25E (82% identical), Caenorhabditis elegans hel-1 (75% identical). Paralogues in human: DDX39B (90% identical), EIF4A1 (33% identical), EIF4A2 (33% identical), DDX3X (32% identical), DDX3Y (31% identical), EIF4A3 (31% identical), DDX23 (30% identical), DDX6 (30% identical), DDX19B (29% identical), DDX42 (29% identical), DDX46 (29% identical), DDX49 (29% identical), and 26 more.
Diseases named in the same sentence as DDX39A in open-access papers:
DDX39A is named in the same sentence as 37 diseases in open-access papers, as found by Europe PMC text mining. Sharing a sentence is not in itself a finding about the gene and the disease. The quoted sentences say what the papers report.
hepatocellular carcinoma (8 papers, 2018 to 2025). A malignant tumor that arises from hepatocytes. "DDX39A promotes the growth and metastasis of hepatocellular carcinoma by facilitating the accumulation of β-catenin in the nucleus and participating in the activation of Wnt/β-catenin pathway." (PMID 41153010, 2025).
lung squamous cell carcinoma (5 papers, 2016 to 2024). "DDX39A up-regulation in lung squamous cell cancer has been demonstrated to promote tumor growth." (PMID 27354262, 2016).
melanoma (5 papers, 2012 to 2021). A malignant, usually aggressive tumor composed of atypical, neoplastic melanocytes. "By using GEO database analysis, we identified the DDX39A gene as a differentially expressed gene between melanoma and pigmented nevus tissue." (PMID 32903487, 2020).
prostate carcinoma (4 papers, 2020 to 2025). A carcinoma that arises from epithelial cells of the prostate gland. "Similarly, prostate cancer tissues have been found to have higher amounts of DDX39A than tissues of benign prostatic hyperplasia, according to Western blot assays." (PMID 38994627, 2024).
colorectal cancer (3 papers, 2019 to 2025). A primary or metastatic malignant neoplasm that affects the colon or rectum. "Additionally, DDX39A facilitates the proliferation, 3D organoid formation and cell cycle progression of colorectal cancer cells." (PMID 41153010, 2025).
cervical cancer (1 paper, 2022). A primary or metastatic malignant neoplasm involving the cervix. "Univariate Cox regression analysis screened 7 genes (FZR1, IMPDH1, HNRNPCL2, PCNA, GPKOW, XPA, and DDX39A) that were associated with the cervical cancer prognosis." (PMID 35909901, 2022). "Identification of KIN-related prognostic genes in cervical cancer revealed that a total of 5 genes (FZR1, IMPDH1, GPKOW, XPA, and DDX39A) were constructed for this risk score, and the results showed that CTLA4 expressions were negatively correlated with the risk score." (PMID 35909901, 2022).
heart failure (1 paper, 2021). Inability of the heart to pump blood at an adequate rate to meet tissue metabolic requirements. "To get the robust gene signature in heart failure, we overlapped genes from LASSO and SVM-RFE and got six gene signatures, including PALLD, DDX39A, CD164, CLDND1, SLC38A2, and CALU." (PMID 34926621, 2021).
influenza (1 paper, 2022). An acute viral infection of the respiratory tract, occurring in isolated cases, in epidemics, or in pandemics; it is caused by serologically different strains of viruses (influenzaviruses) designated A, B, and C, has a 3-day incubation period, and usually lasts for 3 to 10 days. "Based on our data, we speculated that DDX39B and DDX39A may regulate influenza vRNP activity through their interaction with NP." (PMID 36084138, 2022).
tongue squamous cell carcinoma (1 paper, 2025). A squamous cell carcinoma that arises from the tongue. "DDX39A promotes the proliferation and invasion of tongue squamous cell carcinoma cells." (PMID 41153010, 2025).
cancer (13 papers, 2014 to 2025). A tumor composed of atypical neoplastic, often pleomorphic cells that invade other tissues. "Our analysis revealed that genes such as ARID3A, CCNA2, and DDX39A were consistently and significantly overexpressed in cancer tissues." (PMID 40735323, 2025). "DDX39A, a paralog of DDX39B, has been shown to have cancer-promoting activity in lung squamous-cell carcinoma, urinary bladder cancer, human malignant pleural mesothelioma, and hepatocellular carcinoma." (PMID 33436563, 2021). "DDX39A is a RNA helicase and Telomeric Repeat Factor 2 (TRF2)-interacting protein with suspected roles in both cancer and longevity." (PMID 32564008, 2020). "DDX39A, as an RNA splicing factor, may increase RNA helicase activity, promote the splicing and transport of mRNA of epithelial-mesenchymal transition (EMT)-related genes, and increase their expression, and promotes cancer metastasis." (PMID 41153010, 2025).
tumor (11 papers, 2016 to 2025). "DDX39A is a promising biomarker and therapy target for OS, and coumestrol exerts tumor suppressive properties in OS via inhibiting DDX39A." (PMID 41153010, 2025). "Therefore, more extensive analysis with larger groups of cell lines and tumor samples from patients treated with retinoids is needed to validate the possible role of DDX39A protein as a biomarker of response to retinoids besides its indicated prognostic value." (PMID 31188873, 2019). "In addition, DDX39A may affect a variety of immune cells and induce tumor immune escape in the ccRCC immune microenvironment." (PMID 34421357, 2021). "Results of IHC analyses of DDX39A, HMGA1, HMGA2, HOXC9, and PBX1 expression in tumor samples." (PMID 31188873, 2019). "The obtained results were therefore in conflict with previously published research that analyzed DDX39A protein levels in 2 reference NBL cell lines and primary tumor samples before and after treatment with 10 μM ATRA and observed higher DDX39A expression in undifferentiated cells." (PMID 31188873, 2019). "In the external dataset GSE16088, DDX39A and U2AF1 were significantly highly expressed in tumor samples, and RAB20 was significantly lowly expressed in tumor tissues, and PPP1R3 was significantly highly expressed in tumor samples, which was inconsistent with the results in the GSE39262 dataset." (PMID 41153010, 2025).
DDX39A also shares sentences with these, for which no sentence is quoted: breast carcinoma (3 papers); bladder cancer (2); gastrointestinal stromal tumor (2); liver cancer (2); pancreatic cancer (2); benign prostatic hyperplasia (1); bladder urothelial carcinoma (1); breast adenocarcinoma (1); breast tumor (1); cholestasis (1); clear cell renal cell cancer (1); gastric cancer (1); immune dysfunction (1); infection (1); liver disease (1); lung carcinoma (1); lymphoma (1); malignant mesothelioma (1); myeloma (1); nevus (1); osteosarcoma (1); phospholipidosis (1); pleural mesothelioma (1); renal carcinoma (1); sarcoma (1); Tetralogy of Fallot (1).